CFTR (CF transmembrane conductance regulator)
Diseases named in the same sentence as CFTR in open-access papers (continued):
Sharing a sentence is not in itself a finding about the gene and the disease.
cystic fibrosis (continued). "Dysfunctional CFTR altered the susceptibility to severe acute respiratory syndrome coronavirus-2 (SARS-CoV-2) infection, resulting in the reduced viral entry and replication in cystic fibrosis cells, and CFTR inhibitors displayed antiviral activity against SARS-CoV-2 in vitro." (PMID 39205282, 2024). "The treatment of patients with CF (pwCF) has been revolutionized by the efficacy of cystic fibrosis transmembrane conductance regulator (CFTR) modulator therapy." (PMID 39330416, 2024). "Modern treatments for CF mainly target the cystic fibrosis transmembrane conductance regulator (CFTR)." (PMID 38790931, 2024). "Cystic fibrosis (OMIM 219700) is a monogenic disorder, which is directly caused by over 2500 gene variants in the CF Transmembrane Conductance Regulator (CFTR) gene (OMIM, 602421)." (PMID 39329970, 2024). "The cotranslational misfolding of the cystic fibrosis transmembrane conductance regulator chloride channel (CFTR) plays a central role in the molecular basis of cystic fibrosis." (PMID 39091758, 2024). "Allergic bronchopulmonary aspergillosis (ABPA) results from complex hypersensitivity reactions to Aspergillus fumigatus, which often occur in patients with asthma, cystic fibrosis, or CF transmembrane conductance regulator (CFTR)-related disorders." (PMID 39131200, 2024). "Limited understanding of the diversity of variants in the cystic fibrosis transmembrane conductance regulator (CFTR) gene across ancestries hampers efforts to advance molecular diagnosis of cystic fibrosis." (PMID 38515211, 2024). "For example, in the treatment of CF, an inherited lung disease, mRNA–LNP technology is used to introduce an mRNA sequence that can repair mutations in the cystic fibrosis transmembrane conductance regulator (CFTR) gene." (PMID 39337651, 2024). "In cystic fibrosis, there is abnormal translocation and function of the cystic fibrosis transmembrane conductance regulator (CFTR) and an upregulation of the epithelial sodium channel (ENaC)." (PMID 39413095, 2024). "Cystic fibrosis is an autosomal recessive genetic disorder of the cystic fibrosis transmembrane conductance regulator (CFTR) protein, which reduces chloride and sodium ion transport across cell membrane of epithelial barriers." (PMID 37548691, 2024). "The care for cystic fibrosis has dramatically changed with the development of modulators, correctors, and potentiators of the CFTR molecule, which lead to improved clinical status of most people with CF (pwCF)." (PMID 39620135, 2024). "There is limited evidence of the impact of cystic fibrosis transmembrane conductance regulator (CFTR) modulators on exercise capacity in children with CF." (PMID 38375430, 2024). "Highly effective modulator therapies (HEMT) that correct cystic fibrosis transmembrane regulator (CFTR) dysfunction have been a breakthrough in the management of CF disease, improving outcomes and prolonging life." (PMID 39606469, 2024). "The four cystic fibrosis transmembrane conductance regulator (CFTR) modulators, ivacaftor, lumacaftor, tezacaftor, and elexacaftor, have revolutionised the treatment of CF by direct action on the protein target behind the disease’s development." (PMID 39196336, 2024). "In particular, the ion transport of SLC26A4 is different from that of cystic fibrosis transmembrane conductance regulator (CFTR) in various organs and tissues, including the lung, kidney, thyroid, inner ear, parotid duct, and liver." (PMID 38673775, 2024). "Their ability to increase CFTR function while reducing cellular stress and inflammation, together with their favorable safety profile and accessibility could make them valuable additions to cystic fibrosis treatment options." (PMID 39043981, 2024). "Loss of function mutations in the cystic fibrosis transmembrane conductance regulator (CFTR) gene lead to CF, a devastating genetic disease affecting greater than 70,000 patients worldwide." (PMID 37502997, 2023).
cystic fibrosis (continued). "Cystic fibrosis is an autosomal recessive disorder of the CF transmembrane conductance regulator (CFTR) gene." (PMID 37905296, 2023). "Cystic fibrosis transmembrane conductance regulator (CFTR) modulators improve clinical outcomes with varied efficacies in patients with CF." (PMID 36625583, 2023). "The cystic fibrosis transmembrane conductance regulator (CFTR) is an anion channel that regulates salt and water homeostasis across epithelial membranes." (PMID 37843282, 2023). "Treatment of cystic fibrosis has been revolutionized by the use of cystic fibrosis transmembrane conductance regulator (CFTR) protein modulators such as elexacaftor/tezacaftor/ivacaftor (ETI) triple therapy." (PMID 37525180, 2023). "While cystic fibrosis transmembrane regulator (CFTR) modulators show promising results for improving CF lung disease, data on their safety in pregnancy are still limited." (PMID 36836003, 2023). "Additionally, molecular therapies developed to treat cystic fibrosis by increasing CFTR activity may be applicable for colorectal cancer tumors expressing low levels of CFTR." (PMID 36765944, 2023). "Cystic fibrosis transmembrane conductance regulator (CFTR) is a cAMP-regulated chloride (Cl−) channel expressed at the apical plasma membrane (PM) of epithelial cells." (PMID 38067172, 2023). "In the context of cystic fibrosis, defects in the cystic fibrosis transmembrane conductance regulator (CFTR) result in dehydrated and viscous mucus, a decrease in mucociliary clearance, and chronic inflammation." (PMID 37942787, 2023). "A severely defective quantity or activity of the CFTR protein originates in cystic fibrosis, targeting respiratory, pancreatic, and vas deferens epithelia." (PMID 37761921, 2023). "The NPD values show a gradient of abnormalities, from CF patients with inadequate pancreas through CF patients with sufficient pancreas to cystic fibrosis transmembrane regulator-related disorders (CFTR-RD) heterozygotes and healthy individuals." (PMID 37719614, 2023). "In cystic fibrosis, defects in the CF transmembrane conductance regulator (CFTR) channel lead to an acidic airway surface liquid (ASL), which compromises innate defence mechanisms, predisposing to pulmonary failure." (PMID 37967223, 2023). "While homozygous carriers of CFTR mutations generally develop cystic fibrosis, heterozygous carriers do not necessarily; however, they often exhibit an increased risk for pancreatitis and associated pancreatic damage characterized by elevated mucus levels, fibrosis, and cyst formation." (PMID 36609875, 2023). "The majority of the enrolled CF patients were receiving Cystic Fibrosis Transmembrane Conductance Regulator (CFTR) therapy (72.7%), and most of them had hyperthymic temperament predominance (29.1%)." (PMID 37190584, 2023). "CFTR modulators that target the underlying defect, such as the triple combination Elexacaftor/Tezacaftor/Ivacaftor (ETI), are available for approximately 90% of people with cystic fibrosis (pwCF) aged 12 years and older with at least one copy of the del508 mutation." (PMID 37958017, 2023). "As for other membrane proteins such as CFTR (cystic fibrosis transmembrane conductance regulator) and ATP7B (copper-transporting ATPase 2), non-polar-to-polar missense variants in transmembrane domains destabilize the structure, leading to diseases such as cystic fibrosis and Wilson’s disease." (PMID 38066485, 2023). "Cystic fibrosis is a hereditary disorder characterized by the malfunctioning of the cystic fibrosis transmembrane conductance regulator (CFTR) gene." (PMID 38024076, 2023). "CF is inherited by the autosomal recessive transmission of a mutation in CFTR, a gene located on chromosome 7q31.2, which encodes the cystic fibrosis transmembrane conductance regulator (CFTR) protein." (PMID 37511654, 2023).
cystic fibrosis (continued). "CF is an autosomal recessive disease caused by a defect in the CFTR gene located in the 7q31.2 chromosome, producing cystic fibrosis transmembrane conductance regulator (CFTR protein)." (PMID 36969859, 2023). "Due to the study of cystic fibrosis in children, primary CFTR dysfunction has been widely discussed, but there are few studies on acquired CFTR dysfunction in CRS children." (PMID 36662267, 2023). "CF mice that lack the cystic fibrosis transmembrane conductance regulator (CFTR) protein (CFTR S489X-; FABP-hCFTR) were infected intratracheally with either 107, 106, or 105 Ax CFU and monitored daily for up to 4 d (96 h) for signs of distress and morbidity." (PMID 37255468, 2023). "Highly effective cystic fibrosis transmembrane conductance regulator (CFTR) modulator therapies (HEMT), including elexacaftor-tezacaftor-ivacaftor, correct the underlying molecular defect causing CF." (PMID 37795027, 2023). "A relevant example comes from cystic fibrosis, characterized by defective CFTR but also to secondary failure to activate ENaC and reabsorb Na+." (PMID 36648486, 2023). "Moreover, the steps rate-limiting to CFTR activity in unaffected individuals and patients with cystic fibrosis, and thus most likely to be sensitive to pharmacological modulation, remain unclear." (PMID 36949202, 2023). "The combination of two molecules involved in refining CFTR protein folding (elexacaftor/tezacaftor) and another molecule to potentiate CFTR ion gating function (ivacaftor) has improved lung function, sweat chloride levels, and overall quality of life in people with cystic fibrosis (pwCF)." (PMID 37830825, 2023). "In the precision medicine era of cystic fibrosis, therapeutic interventions, by the so-called modulators, target the cystic fibrosis transmembrane conductance regulator (CFTR) protein." (PMID 37761921, 2023). "CFTR, responsible for the monogenic autosomal recessive cystic fibrosis, impacts 1 in 3500 global live births." (PMID 37895887, 2023). "An interesting proof-of-concept study of the intranasal DOTAP liposomes targeting the CFTR gene that overexpressed in lung parenchyma of cystic fibrosis patients demonstrated the safety in the first-in-human trial application." (PMID 37483515, 2023). "In the last decade, the availability of Cystic Fibrosis Transmembrane conductance Regulator (CFTR) modulators has changed the clinical history of Cystic Fibrosis." (PMID 37420288, 2023). "The new breakthrough cystic fibrosis drug combination of ivacaftor (IVA), tezacaftor (TEZ), and elexacaftor (ELX), namely “caftor” drugs, directly modulates the activity and trafficking of the defective CF transmembrane conductance regulator protein (CFTR) underlying the CF disease." (PMID 36831163, 2023). "A few years later, the introduction of cystic fibrosis transmembrane regulator (CFTR) modulators opened new horizons for CF patients." (PMID 36836003, 2023). "Allosteric or orthosteric binding of VX-809 and/or VX-445 folding correctors to TMD1/2 can rescue kinetically trapped CFTR posttranslational folding intermediates of cystic fibrosis mutants of NBD1 or TMD1 by global rewiring inter-domain allosteric-networks." (PMID 37891162, 2023). "Ivacaftor is a potentiator of the chloride ion transporter cystic fibrosis transmembrane conductance regulator (CFTR) that works by improving the function of the CFTR protein in cystic fibrosis patients with a gating defect." (PMID 36809189, 2023). "The advent of highly effective cystic fibrosis transmembrane conductance regulator (CFTR) modulator therapy has led to an unprecedented improvement in the lives of people with CF (pwCF)." (PMID 37469865, 2023). "In cystic fibrosis, this compound improves patients’ symptoms by recovering the activity of a number of mutants of the cystic fibrosis transmembrane conductance regulator (CFTR)." (PMID 38203723, 2023).
cystic fibrosis (continued). "IMPORTANCE CFTR modulators have been developed to correct and/or enhance CFTR activity in patients with specific cystic fibrosis genotypes." (PMID 36625583, 2023). "Alterations in CFTR cause cystic fibrosis, a fatal disease without a cure." (PMID 36949202, 2023). "Search terms included cystic fibrosis, nutrition, enteral nutrition, parenteral nutrition and CFTR modulators, in combination with neonate, newborn, infant and preterm infant." (PMID 36771186, 2023). "Samples collected from newborn wild-type (WT) and cystic fibrosis transmembrane conductance regulator (CFTR) null piglets revealed that distinct proteins were bound to the mucus as opposed to the ones easily washed off and associated with the airway liquid." (PMID 36927357, 2023). "Restoring cystic fibrosis transmembrane conductance regulator (CFTR) expression in surface columnar epithelial cells is necessary for the correction of the CF airway phenotype." (PMID 38077224, 2023). "Cystic fibrosis is an example where novel CFTR modulators such as Kaftrio® and Kalydeco® are only available as SODFs." (PMID 36928840, 2023). "Another CLK inhibitor (CaNDY) has shown promise in correcting the mis-splicing of the CFTR gene in cystic fibrosis." (PMID 37895245, 2023). "This is also the case for the cystic fibrosis transmembrane conductance regulator (CFTR or ABCC7), in which mutations cause cystic fibrosis, a severe genetic disease affecting around 70,000 patients world-wide." (PMID 36555865, 2022). "Another EQA provider, CF Network, focuses on one specific gene, Cystic Fibrosis Transmembrane conductance Regulator (CFTR)." (PMID 35954349, 2022). "Cystic fibrosis transmembrane conductance regulator (CFTR) potentiators are small molecules developed to treat the genetic disease cystic fibrosis." (PMID 34644413, 2022). "A workup for cystic fibrosis (sweat Cl− and genetic tests for 14 CFTR mutations) was negative." (PMID 35163670, 2022). "Mutations in the cystic fibrosis transmembrane conductance regulator (CFTR) gene often lead to cystic fibrosis, a lethal autosomal-recessive inherited disease." (PMID 34977268, 2022). "Several studies have been reported demonstrating that microRNAs are involved in Cystic Fibrosis, a genetic disease caused by alteration of production and/or biological activity of the gene coding the chloride channel CFTR (Cystic Fibrosis Transmembrane Conductance Regulator)." (PMID 36012615, 2022). "In this scenario, the identification of agents endowed with a dual-target activity (i.e., antibacterial and antioxidant or antioxidant and CFTR-rescuing activities combined in one molecule) may lead to increased therapeutic benefits for cystic fibrosis patients." (PMID 36293130, 2022). "CF is an autosomal recessive disorder that occurs in 1 in 2500 births and is the result of at least one or more of 1500 possible mutations in the CFTR (cystic fibrosis transmembrane conductance regulator) gene." (PMID 35744765, 2022). "Cystic fibrosis is a genetic disorder caused by mutations to the cystic fibrosis transmembrane conductance regulator (CFTR) gene, which in turn leads to reduced or absent CFTR protein function to move anions across the surface of the epithelium." (PMID 35574458, 2022). "An example is that of the cystic fibrosis transmembrane conductance regulator (CFTR) which, when mutated, contributes to CF." (PMID 35418593, 2022). "Overweight and obesity is expected to increase in prevalence in the CF population, as highly effective cystic fibrosis transmembrane regulator (CFTR) modulator use becomes widespread." (PMID 35215485, 2022). "The aim of this study was to explore whether there is a relationship between CFTR-modulator drugs and the psychological and social aspects of the lives of individuals with cystic fibrosis including: career, relationships, family planning, and psychological functioning." (PMID 35062937, 2022).
cystic fibrosis (continued). "The pulmonary ionocytes express Forkhead box I1 (FoxI1), multiple subunits of the V-ATPase (Atp6v1c2 and Atp6v0d2), Cochlin, ASCL3, and the cystic fibrosis transmembrane conductance regulator (CFTR)." (PMID 35562719, 2022). "A further limitation is the generalisability of these results to the CF population in the era of new cystic fibrosis transmembrane conductance regulator (CFTR) modulators." (PMID 33975926, 2022). "Moreover, the authors suggested that reduced ALOX15B expression may be due to the cystic fibrosis gene CF transmembrane conductance regulator (CFTR), impairing macrophage function." (PMID 36438817, 2022). "It was found that the cystic fibrosis transmembrane conductance regulator (CFTR), which causes CF when defective due to mutations, is important in the regulation of CD4+ T-cells." (PMID 35893126, 2022). "Lung transplantation is often a necessary step in the current care of patients with cystic fibrosis, although the development of new therapies, such as CFTR (cystic fibrosis transmembrane conductance regulator) modulators, seem consistent with pregnancy and may obviate the need for transplantation." (PMID 36013030, 2022). "Cystic fibrosis is a fatal chronic pulmonary infection that occurs due to a defect in transmembrane protein which is known as cystic fibrosis transmembrane conductance regulator (CFTR) which regulates chloride ion secretion." (PMID 35892224, 2022). "This issue will become even more important in CF patients treated with highly effective cystic fibrosis transmembrane (CFTR) modulators." (PMID 35972283, 2022). "Cystic fibrosis is a heritable disease characterized by dysfunction of the CFtransmembrane conductance regulator (CFTR) epithelial chloride channel." (PMID 35012387, 2022). "The etiology of these manifestations is likely multifactorial, resulting from cystic fibrosis transmembrane conductance regulator (CFTR) dysfunction, a high-fat CF diet, and the use of antibiotics." (PMID 35160099, 2022). "The advent of Cystic fibrosis transmembrane receptor (CFTR) modulators in 2012 was a critical event in the history of cystic fibrosis treatment." (PMID 35408875, 2022). "In addition, we have defined organoid culture conditions, with the growth factor/cytokine combination neuregulin-1β and interleukin-1β, which enabled consistent detection of CFTR modulator responses in nasal-airway organoid cultures from subjects with cystic fibrosis." (PMID 35922154, 2022). "Cystic fibrosis transmembrane conductor regulator (CFTR); Phenylalanine 508 deletion mutation (Phe508del); Delta phenylalanine 508 deletion mutation-cystic fibrosis transmembrane conductor regulator gene (deltaPhe508-CFTR); Cystic fibrosis." (PMID 36284811, 2022). "Although cystic fibrosis patients are not bona fide immune-suppressed individuals, their deficiency in clearing lung pathogens such as P.a clearly indicates that new strategies are welcome to supplement already successful CFTR-targeted treatments." (PMID 35955566, 2022). "CF is a genetic disorder due to the dysfunction of cystic fibrosis transmembrane conductance regulator (CFTR)." (PMID 35764957, 2022). "Lumacaftor/Ivacaftor (LUM-IVA), a cystic fibrosis transmembrane conductance regulator (CFTR) protein corrector-potentiator combination, improves lung function and reduces pulmonary exacerbations (PEx) in F508del homozygous CF patients." (PMID 36266606, 2022). "In our cohort, three patients had CFTR gene mutations (one homozygous, one compound heterozygous, and one complex heterozygous genotype); none of these patients manifested the clinical features of cystic fibrosis." (PMID 35844741, 2022). "CFTR is an anion channel transporting Cl− and HCO3− across the apical membrane of epithelial cells and its mutations cause cystic fibrosis and chronic pancreatitis." (PMID 35774225, 2022).